BLOC1S5 (biogenesis of lysosomal organelles complex 1 subunit 5)
Description:
Component of the BLOC-1 complex, a complex that is required for normal biogenesis of lysosome-related organelles (LRO), such as platelet dense granules and melanosomes. In concert with the AP-3 complex, the BLOC-1 complex is required to target membrane protein cargos into vesicles assembled at cell bodies for delivery into neurites and nerve terminals. The BLOC-1 complex, in association with SNARE proteins, is also proposed to be involved in neurite extension. Plays a role in intracellular vesicle trafficking.
Synonyms: MUTED; MU; dJ303A1.3; BLOS5; HPS11
Tractability: PROTAC: ubiquitination databases record sites on it.
Gene: Protein-coding gene on chromosome 6 (8,013,566 to 8,064,414, reverse strand). Ensembl gene ENSG00000188428.
Subcellular location (Human Protein Atlas): Vesicles
Gene Ontology:
Molecular function: protein binding; AP-3 adaptor complex binding
Biological process: endosome to melanosome transport; melanosome transport; positive regulation of pigment cell differentiation; anterograde axonal transport; anterograde synaptic vesicle transport; melanosome organization; neuron projection development; gene expression; otolith development; swimming behavior
Cellular component: BLOC-1 complex; transport vesicle; axon cytoplasm; microvesicle
Genetic constraint (gnomAD): Loss-of-function variants: 24 observed, 20.69 expected, observed/expected ratio (o/e) 1.16, 90% interval 0.84 to 1.62. The upper end of that interval is the gene's LOEUF score, 1.62, which puts it in group 6 of 6, group 1 being the genes least tolerant of losing a copy. Missense variants: 206 observed, 202.68 expected, observed/expected ratio (o/e) 1.02, 90% interval 0.91 to 1.14. Synonymous variants: 79 observed, 68.74 expected, observed/expected ratio (o/e) 1.15, 90% interval 0.96 to 1.39.
Gene-disease validity (ClinGen):
ClinGen rates the evidence that BLOC1S5 causes each of these diseases.
Hermansky-Pudlak syndrome 11 (autosomal recessive): Definitive.
Homologues: Orthologues: chimpanzee BLOC1S5 (100% identical), rabbit BLOC1S5 (86% identical), pig BLOC1S5 (85% identical), rat Bloc1s5 (81% identical), guinea pig BLOC1S5 (81% identical), mouse Bloc1s5 (76% identical), dog BLOC1S5 (52% identical), zebrafish bloc1s5 (44% identical), Drosophila melanogaster Muted (17% identical).
Diseases named in the same sentence as BLOC1S5 in open-access papers:
BLOC1S5 is named in the same sentence as 4 diseases in open-access papers, as found by Europe PMC text mining. Sharing a sentence is not in itself a finding about the gene and the disease.
BLOC1S5 shares sentences with these, for which no sentence is quoted: albinism (1 paper); infection (1); lung adenocarcinoma (1); ovarian carcinoma (1).